RAD23A (RAD23 nucleotide excision repair protein A)
Description:
Multifunctional protein that participates in histone H4K20 demethylation, DNA repair, ubiquitin-dependent protein degradation, transcriptional regulation, and viral replication. Specifically demethylates mono-, di- and trimethylated 'Lys-20' of histone H4 (H4K20me1, H4K20me2, H4K20me3, respectively) into unmethylated forms. Activates the transcription of coding genes by demethylating H4K20me1 and the transcription of repetitive elements by demethylating H4K20me3. Involved in modulation of proteasomal degradation. Binds to 'Lys-48'-linked polyubiquitin chains in a length-dependent manner and with a lower affinity to 'Lys-63'-linked polyubiquitin chains. Proposed to be capable to bind simultaneously to the 26S proteasome and to polyubiquitinated substrates and to deliver ubiquitinated proteins to the proteasome. Involved in nucleotide excision repair, is considered functionally equivalent to RAD23B in global genome nucleotide excision repair (GG-NER) through its association with XPC. In vitro, the XPC-RAD23A complex demonstrates NER activity. Can stabilize XPC (By similarity). (Microbial infection) Involved in -dependent replication of HIV-1 in non-proliferating cells and primary macrophages. Required for the association of HIV-1 Vpr with the host proteasome.
Synonyms: HR23A; hHR23A; MGC111083
Tractability: PROTAC: UniProt records ubiquitination sites on it; ubiquitination databases record sites on it; its protein half-life has been measured.
Gene: Protein-coding gene on chromosome 19 (12,945,848 to 12,953,646, forward strand). Ensembl gene ENSG00000179262.
Subcellular location: Nucleus
Subcellular location (Human Protein Atlas): Nucleoplasm; Cytosol; Golgi apparatus; Vesicles
Pathways (Reactome):
DNA Repair: DNA Damage Recognition in GG-NER; Formation of Incision Complex in GG-NER
Metabolism of proteins: Josephin domain DUBs
Gene Ontology:
Molecular function: histone H4K20 demethylase activity; kinase binding; polyubiquitin modification-dependent protein binding; protein binding; ubiquitin-specific protease binding; single-stranded DNA binding; damaged DNA binding
Biological process: nucleotide-excision repair; positive regulation of cell cycle; positive regulation of proteasomal ubiquitin-dependent protein catabolic process; positive regulation of viral genome replication; protein destabilization; regulation of proteasomal ubiquitin-dependent protein catabolic process; proteasome-mediated ubiquitin-dependent protein catabolic process; chromatin remodeling
Cellular component: cytoplasm; nucleoplasm; nucleus; protein-containing complex; cytosol
Genetic constraint (gnomAD): Loss-of-function variants: 16 observed, 44.42 expected, observed/expected ratio (o/e) 0.36, 90% interval 0.24 to 0.55. The upper end of that interval is the gene's LOEUF score, 0.55, which puts it in group 2 of 6, group 1 being the genes least tolerant of losing a copy. Missense variants: 380 observed, 498.43 expected, observed/expected ratio (o/e) 0.76, 90% interval 0.7 to 0.83. Synonymous variants: 217 observed, 209.46 expected, observed/expected ratio (o/e) 1.04, 90% interval 0.93 to 1.16.
Homologues: Orthologues: chimpanzee RAD23A (100% identical), macaque RAD23A (99% identical), dog RAD23A (97% identical), pig RAD23A (96% identical), rat Rad23a (95% identical), mouse Rad23a (95% identical), guinea pig RAD23A (93% identical), zebrafish rad23aa (65% identical), Caenorhabditis elegans rad-23 (36% identical), Drosophila melanogaster CG10694 (27% identical). Paralogues in human: RAD23B (63% identical).
Diseases named in the same sentence as RAD23A in open-access papers:
RAD23A is named in the same sentence as 16 diseases in open-access papers, as found by Europe PMC text mining. Sharing a sentence is not in itself a finding about the gene and the disease. The quoted sentences say what the papers report.
ovarian carcinoma (2 papers, 2025). A malignant neoplasm originating from the surface ovarian epithelium. "A study in investigating ovarian cancer resistance to niraparib revealed that H4K12 lactylation upregulates RAD23A via super-enhancers, potentiating DNA repair and fostering chemoresistance." (PMID 41561760, 2025). "While elevated RAD23A enhances ovarian cancer cell resistance to niraparib." (PMID 41561760, 2025). "In ovarian cancer, transcription levels of critical enzymes in glycolysis particularly LDHA and pyruvate kinase M show significant positive correlations with RAD23A." (PMID 41561760, 2025).
coronary artery disease (1 paper, 2022). "We entered FBXO7, RAD23A, and MKRN1 into the camp database and eventually identified 11 drugs that could be used to treat coronary artery disease, including doxorubicin, gabapentin, suxibuzone, prasterone, kawain, 5255229, decline, nalbuphine, MK-801, trimethoprim, and GW-8510." (PMID 35799780, 2022).
frontotemporal dementia (1 paper, 2022). Frontotemporal dementia (FTD) comprises a group of neurodegenerative disorders, characterized by progressive changes in behavior, executive dysfunction and language impairment, as a result of degeneration of the medial prefrontal and frontoinsular cortices. "Association of SOD1 with module-1 proteins (PSMD2, ADRM1, RAD23A) were involved in ALS15-type with or without Frontotemporal dementia." (PMID 34918006, 2022).
hepatocellular carcinoma (1 paper, 2023). A malignant tumor that arises from hepatocytes. "screened potential autoantibody-based markers for hepatocellular carcinoma (HCC) and found that the AUC of an immunodiagnostic model including 6 TAAbs (RAD23A, CAST, RUNX1T1, PAIP1, SARS, PRKCZ) were 0.835 and 0.788 in the training and validation sets, respectively." (PMID 37251926, 2023).
morbid obesity (1 paper, 2021). An excess of body weight, normally defined as an individual with a body mass index greater than 35 or a body weight greater than one hundred percent of ideal body weight. "Nevertheless, the expression of some of these ERAD-related genes, such as RAD23A, which was higher in SC preadipocytes from NG individuals with simple obesity as compared to lean individuals, decreased in the transition from NG to T2D in obesity, an effect that was also observed in morbid obesity." (PMID 34545810, 2021).
cancer (8 papers, 2012 to 2024). A tumor composed of atypical neoplastic, often pleomorphic cells that invade other tissues. "Previous pan-carcinoma analyses have indicated a significant positive correlation of RAD23A in various cancers." (PMID 38629071, 2024). "Except for UVM, CHOL, UCS, SKCM, MKRN1 was significantly positively correlated with RAD23A in the remaining cancers." (PMID 35799780, 2022). "It was found that the expression values of FBXO7 were also significantly and positively correlated with the degree of CD8+ T cell infiltration in several cancers, followed by RAD23A and MKRN1." (PMID 35799780, 2022). "MKRN1 was significantly positively correlated with RAD23A in the remaining cancers except for MESO, LGG, UCS, CHOL, READ, and BRCA." (PMID 35799780, 2022). "rAD23A increases cancer chemoresistance and the chance of recurrence by upregulating autophagy." (PMID 35799780, 2022). "FBXO7, RAD23A, and MKRN1 are significantly associated with CD8+ T cells in CAD and multiple cancers and may act through immune responses in CAD and cancer." (PMID 35799780, 2022). "ATP1A1, KMT2E and WASF2 were known as the hallmarker of cancers and overexpression of these genes promote the survival of cancer cells, while RAD23A acts as a negative regulator of anti-virus response and might correlate directly with the HPV infection." (PMID 36420261, 2022). "Rad23A was connected via the nodes p300 and CBP to the other nodes in the network, whereas Smad3 was connected to a variety of nodes which also included important cancer-associated TFs such as c-Myc, Runt-related factors, and Smad factors." (PMID 27092172, 2016). "This provides a new theory to study the methylation process of FBXO7 and RAD23A and improve potential CAD immune efficacy in cancer patients." (PMID 35799780, 2022). "In addition, we found that FBXO7, RAD23A, and MKRN1 were significantly positively correlated in cardiac tissues and most cancers." (PMID 35799780, 2022). "We next analyzed the correlation between FBXO7, RAD23A, and MKRN1 in different cancers." (PMID 35799780, 2022). "FBXO7, RAD23A and MKRN1 may act as hub genes linking CAD and cancer in terms of immunity." (PMID 35799780, 2022).
infection (3 papers, 2010 to 2025). The state of being infected such as from the introduction of a foreign agent such as serum, vaccine, antigenic substance or organism. "To ensure that we can replicate the effects of Rad23A and Rad23B knock-down on HCV JcR2a infection with an untagged virus, we performed focus-forming unit (FFU) assays using the parental virus of JcR2a, Jc1, in Huh-7.5 cells." (PMID 38230952, 2024).
tumor (3 papers, 2012 to 2024). "The results showed that, compared to adjacent non-tumor tissues, the expression of RAD23A, SAC3D1, and PSIP1 was significantly upregulated in OS tissues." (PMID 38629071, 2024). "Thus the reduction of RAD23A with longevity could inhibit CHEK1 degredation and allow promotion of tumor growth and therapy resistance." (PMID 31652257, 2019).
RAD23A also shares sentences with these, for which no sentence is quoted: breast carcinoma (1 paper); breast tumors (1); esophageal squamous cell carcinoma (1); gastrointestinal tumors (1); HIV-1 infection (1); lung adenocarcinoma (1); non-small cell lung carcinoma (1); Obesity (1).